IL6 (interleukin 6)
Diseases named in the same sentence as IL6 in open-access papers (continued):
Sharing a sentence is not in itself a finding about the gene and the disease.
cancer (continued). "A study demonstrated that cytokine mediators and growth factors (IL-1, IL-4, IL-6, TNF-α, IFN-γ, TGF-β) regulate the control of the central nervous system in cancer patients, despite the continual loss of skeletal muscle induced by a number of processes." (PMID 35159388, 2022). "Although IL-6 can induce the activation of AKT in some cancer cells, phosphorylation of AKT is inhibited by IL-6 in hepatocytes." (PMID 35708907, 2022). "Supporting the physiological relevance of our cell system, a role for IL-6 in cancer or inflammation of the colon has been well documented in clinical practice." (PMID 35326545, 2022). "The results showed that the expression levels of IL-6, IL18 and GSDME were positively associated with these compounds, while CASP4 was positively correlated with sensitivity to 26 cancer drugs." (PMID 35246158, 2022). "Cancer associated fibroblasts account for the majority of the solid tumor microenvironment while cancer cells only occupy a small proportion and are capable of secreting cytokines, such as IL-6, which suppress the activity of CD8T cells." (PMID 35480306, 2022). "Few studies focused on older persons, except a cohort study including 2400 American septuagenarians that found associations between higher CRP, IL-6 and TNF with all cancer incidence." (PMID 35406394, 2022). "GRb1 can ameliorate the symptoms of cancer cachexia by reducing TNF-α and IL-6 cytokine levels caused by inflammation in cancer cachectic mice." (PMID 36313365, 2022). "The synergy between p-STAT3 and IL6 in HER2+ BC promotes EMT and cancer stem cells proliferation; it is associated with trastuzumab resistance." (PMID 35248049, 2022). "High levels of IL-6 can promote cancer progression through epigenetic alterations and are associated with a shorter overall survival." (PMID 36362726, 2022). "For instance, therapy resistant CAFs produce and secrete IL-6, which has paracrine effects in cancer cells, thereby promoting chemotherapy resistance." (PMID 35646668, 2022). "Different pro-inflammatory markers, like TNF-α and IL-6, contribute to the pathogenesis of some organ damages and cancer." (PMID 36547085, 2022). "IL-6 serum levels were positively related to the severity of a score, including, in adult patients with gastrointestinal cancer, the six most severe cancer-related symptoms (i.e., fatigue and pain)." (PMID 35335997, 2022). "Allogeneic blood transfusion also promotes invasion of cancer cells through IL-6, VEGF and hepatocyte growth factor (HGF)." (PMID 35884557, 2022). "During cancer cell invasion, inflammatory cytokines, mainly TGFβ, TNFα and IL-6, activate transcription factors such as Smads, NF-κB and Snail, driving EMT forward." (PMID 35884845, 2022). "According to previous studies, IL-6 levels increase substantially in the serum and cancer tissues of GC patients." (PMID 36454780, 2022). "Previous studies have shown that HNRNP is involved in cancer-related pathways, including protein secretion, mitochondrial spindle, G2/M checkpoint, DNA repair, IL6/JAK/STAT3 signaling, and other pathways." (PMID 36061307, 2022). "In conclusion, our data demonstrated that RT prevents against STAT3 excessive activation in skeletal muscle mediated by the overabundance of plasma IL-6 and muscle oxidative stress, a key role to attenuate cancer-induced muscle atrophy." (PMID 35847939, 2022). "Interleukin 6 (IL-6) is one of cytokines that mediate in acute phase reactions, inflammation, and cancer progression." (PMID 36407366, 2022). "IL-6 signaling is involved in the pathogenesis of a number of serious diseases, including chronic inflammation and cancer." (PMID 36015338, 2022). "In conclusion, this study confirmed that the IL-6/JAK/STAT3 signaling pathway is involved in the pathological process of “inflammation–atypical hyperplasia–cancer” in the AOM/DSS-induced UC animal model." (PMID 35946886, 2022).
cancer (continued). "The pro-survival effects of TNF-α on cancer cells, IL-6 overstimulation of Janus kinase/signal transducers and transcriptional pathway activators, and matrix metalloproteinases are thought to be mediated." (PMID 35752767, 2022). "This has also been pointed out in studies on the relationship between IL-6 and gastrointestinal and other cancers, and a role was found for IL-6 in the development and maintenance of neoplastic cells." (PMID 36430792, 2022). "Cancer associated fibroblasts (CAFs) secrete about tenfold higher levels of inflammatory adipocytokines such as MCP-1, IL-6, IL-8, RANTES and SDF-1 (VEGF) than normal fibroblasts." (PMID 34951691, 2022). "In patients with advanced cancer, pro-inflammatory cytokines predominate, leading to the upregulation of IL-1 and increased production of downstream IL-6." (PMID 36430236, 2022). "In particular, interleukin-6 (IL-6) is known to be involved in the interaction between fibroblasts and cancer cells in the irradiated cancer microenvironment, and its role has attracted attention." (PMID 35089951, 2022). "Studies have shown that cancer cells over-express some pro-inflammatory factors, such as interleukin 6 (IL-6) and tumour necrosis factor α (TNF-α), are able to stimulate adipocytes to produce an activated phenotype in a paracrine fashion." (PMID 35280694, 2022). "The miR-921-3p and miR-25-3p carried by EVs in liposarcoma cells promoted the secretion of IL-6, which further aided cancer progression." (PMID 35159299, 2022). "Numerous cytokines such as IL-6, IL-10, IL-23, TNF-α, and TGF-β were found to be associated with carcinogenesis and the development of cancers, functioning as pro- or anti-tumorigenic." (PMID 36140470, 2022). "And then, activated CAFs further accelerated cancer cells diffusion and metastasis by secreting pro-inflammatory IL-6 and IL-8." (PMID 36324128, 2022). "In this review, we will discuss inflammaging in the elderly, specifically concentrating on IL-6 and IL-1b in the context of T lymphocytes, and how inflammation is related to mortality and morbidities, specifically cardiovascular disease and cancer." (PMID 35821823, 2022). "We identified a set of 82 cancer and immune-related genes that divide high- and low-IL6/R pAML samples into high-, medium-, and low-IL6/R clusters by unsupervised hierarchical clustering (clusters 1–3 respectively)." (PMID 36418348, 2022). "The up-regulation of IL-6 in cancer cells is also mediated through NFκB, which in turn can be mediated by CXCL10/CXCR3." (PMID 35884405, 2022). "Recent studies supported our observation and showed that TAMs exhibit high IL-6 expression in various cancers." (PMID 35300689, 2022). "Blockage of IL-6 and IL-8 in combination with nivolumab is being investigated in phase 1 clinical trials for several carcinomas, including HNSCC for IL-8 (clinical trial identifiers #NCT03400332, #NCT04848116, #NCT03999749)." (PMID 35359980, 2022). "Previous studies detected high IL‐6 expression in colorectal M1‐type macrophages during the ‘developing carcinoma’ and ‘metastasis’ processes in the CAC mouse model." (PMID 35363937, 2022). "Persistent activation of NF‐κB in the CD10+GPR77+ CAFs is critical for the paracrine regulation of IL‐6 or IL‐8, which provides a niche for the formation of cancer stem cells." (PMID 34459125, 2021). "The first logistic regression model including IL-6, IL-8, and TNFα showed that elevated IL-6 significantly increased the likelihood of having a diagnosis of cancer (p = 0.0040, odds ratio 3.991)." (PMID 35048057, 2021). "Some factors released in the bone microenvironemnt by cancer and stromal cells, including interleukin‐6 (IL‐6) and tumour necrosis factor α (TNF‐α), are able to induce osteoclast differentiation in vitro independently of RANK activation." (PMID 32955748, 2021).
cancer (continued). "IL-6 upregulation in Gprc5a-knockout mice is identified to explain the promoted metastasis of cancer, in which IL-6 activates the STAT3 signaling pathway and induces the recruitment of MDSC to promote lung metastasis." (PMID 34689842, 2021). "Statins disrupt communication between cancer cells and mesenchymal stromal cells (MSC) by inhibiting CCL3 secreted by cancer cells and IL-6 and CCL2 produced by MSC." (PMID 34858839, 2021). "We demonstrated that markedly higher serum IL-6 levels in cancer patients compared to healthy control individuals and a positive correlation between the serum IL-6 levels with the TNF-α and NF-κB levels." (PMID 33776564, 2021). "Regarding myokines, we assessed irisin, OSM, osteonectin, IL-6, IL-15, and IL-7 on account of evidence supporting the utility of these myokines in the context of cancer prevention and control." (PMID 33555464, 2021). "IL-6 induces programmed cell death protein 1-dependent immunosuppression in cancer, and IL-1β is one of the most important pro-inflammatory mediators involved in chemo-resistance." (PMID 34178667, 2021). "IL-6 promotes cancer development by activating endothelial cells, increasing adhesion molecule expression, and inducing matrix metalloproteinase production." (PMID 34956932, 2021). "These three main signalling pathways, with their own complex and pleiotropic effects, lead to the wide range of functions of IL6 and related cytokines in the healthy organism and in diseases, such as immune disorders and cancer." (PMID 34834425, 2021). "TNF-α and IL-6 are well-known cytokines that provoke cancer cachexia in the C26 adenocarcinoma model, where we measured the serum levels of both." (PMID 34262449, 2021). "IL-6 has been shown to promote Th1, Th2, cytotoxic T cell, and NK cell responses and has recently been attributed to enhancing glycolysis in cancer cell models." (PMID 34830070, 2021). "Some of these genes were also present in the general cancer pathway, including NFkBIA, IL-6 and CXCL8." (PMID 34680349, 2021). "SC144 has been widely used to inhibit the IL‐6 signaling pathways in growth tissues and the sensory nervous system‐mediated cancer pain." (PMID 34231965, 2021). "Elevated IL-6 levels have been reported in patients with various types of cancer, such as breast, pancreatic, colorectal, prostate, and non-small cell lung cancer (NSCLC)." (PMID 34001144, 2021). "Interleukin 6 is known as a multifunctional cytokine that has an influence on the development of cancer diseases." (PMID 33494499, 2021). "The IL-6/JAK/STAT3 pathway plays a key role in the growth and development of many human cancers, and elevated IL-6 levels stimulate the overactivation of JAK/STAT3 signaling, which is usually related to poor patient outcomes." (PMID 34926575, 2021). "As expected, the ability of the IL-6- or cancer supernatant treated moDCs to induce the differentiation of naïve CD4+ T cell into T-bet+ CD4+ T cell was impaired." (PMID 34671021, 2021). "Mechanistically, the deregulated immunity of autoimmune conditions and smoldering protumorigenic inflammation observed in cancer share multiple important features and regulatory molecules, including IL-6." (PMID 34681685, 2021). "Specifically in the context of CRC, IL-6 and TNFα act to mediate inflammation and cancer in the TME." (PMID 34299049, 2021). "IL-6 has been highlighted as a crucial component for the pro-inflammatory signature of the stroma and as a pro-tumorigenic molecule in many types of cancer." (PMID 33902430, 2021). "One such signaling cascade is the IL6 induction of JAK/STAT3 signaling, which has been described to influence cell growth and differentiation, and is, therefore, often implicated in cancer when dysregulated." (PMID 33763387, 2021).
cancer (continued). "An elevated level of TNF-α and IL6 has been found in the serum of cancer patients treated with gemcitabine." (PMID 34771621, 2021). "Numerous studies have demonstrated that the aberrant expression of IL-6 and its receptor correlates with malignant phenotypes of multiple tumors, as well as the diagnosis, prognosis, and treatment of cancer." (PMID 33494738, 2021). "In cancer, increased levels of IL-6 result in increased activation of Jak-Stat3 pathway, which correlates with poor prognosis." (PMID 34376733, 2021). "The molecule is known to induce a pro-tumorous microenvironment, angiogenesis, and metastasis, primarily via signaling through STAT3, making IL6 another attractive target for cancer therapy." (PMID 34064000, 2021). "Pro-inflammatory cytokines, including TNF-α, IL-1, IL-6, are usually increased in many types of cancer." (PMID 34944975, 2021). "At the molecular level, inflammation leads to the production of inflammatory cytokines, such as IL-6, IL-1β, and TNF, which have been associated with cardiovascular disease and several different types of cancer." (PMID 34234868, 2021). "The increased levels of TNF-α and IL-6 in NMSC patients can be introduced as an epiphenomenon of a complex cancer-induced cytokine cascade." (PMID 33461943, 2021). "MDSC-secreted factors that overlap with TREM-1 target genes, including IL-1β, TNF-α, IL-8 and IL-6, have been reported to promote angiogenesis and induce cancer cell migration, invasion, and survival." (PMID 34956864, 2021). "The C26 model of cancer‐induced muscle wasting is known to be mediated by elevated levels of pro‐inflammatory cytokines such as IL‐6." (PMID 34096686, 2021). "More recently, IL-6 has been identified as the key determinant of muscle mass wasting in advanced cancer patients." (PMID 33535496, 2021). "Nevertheless, some results obtained from studies of other cancer types imply that curcumin can inhibit TGF-β1-induced EMT, invasion, and IL-6 expression, and thereby cancer metastasis." (PMID 34834295, 2021). "By contrast, IL6 is a member of a family of cytokines with established roles in acute phase response, inflammation, hematopoiesis, and cancer progression." (PMID 34001994, 2021). "A new subset of CD10+GPR77+CAFs induce cancer stem cells’ (CSCs) enrichment and chemoresistance by secreting IL-6 and CXCL8 in cancer." (PMID 35011369, 2021). "The IL6/JAK/STAT3 pathway is aberrantly hyperactivated in many types of cancer, and is important for human BC development as well as BC metastasis." (PMID 35087836, 2021). "In our study, we showed higher expression of IL-6 in surgical tissue margin compared to cancer tissue." (PMID 33658555, 2021). "Further related clinical trials have indicated that IL-6 blockade therapy effectively improves the function of T cells and the prognosis of patients with cancer." (PMID 34635121, 2021). "In summary, the information gathered in this section supports that the association between IL-6, OSM and EMP observed in cancer cell lines and animal models is relevant in the clinical setting." (PMID 34361105, 2021). "STAT3 inhibitors can inhibit the proliferation and development of cancers by blocking IL-6/STAT3 signaling, suppressing cancer cells proliferation and promoting apoptosis." (PMID 34976809, 2021). "The IL-6 has been reported to be overexpressed in most types of cancers and regulates almost all of the important signaling pathways." (PMID 34200663, 2021). "Similar to IL-6 and TNF-α, TGF-β is associated with a wide range of tumor-inductive or cancer-supportive mechanisms, such as EMT, immune escape, the formation of blood vessels, as well as the suppression of apoptotic pathways." (PMID 33429846, 2021). "IL-6 has been reported to activate STAT3 to promote EMT through the induction of Snail expression in cancers." (PMID 34771643, 2021). "Overall, we found a positive correlation between drug-treated and low IL-6 (in fibroblasts) plus high LC3 plus low p62 in cancer cells (Pearson r = 0.898, p < 0.01)." (PMID 33925189, 2021).
cancer (continued). "Investigation of molecular signaling pathways shows that IL-6 elevates the progression of cancer cells through induction of Raf-MAPK signaling pathway." (PMID 33478512, 2021). "Some of these potentially metastatic CAF-secreted factors involved in EMT have been studied extensively in the past years in multiple cancer types, such as interleukin-6 (IL-6), osteopontin (OPN), hepatocyte growth factor (HGF), and CXCL12." (PMID 34572947, 2021). "Cancer cells and CAFs release similar inflammatory cytokines such as IL-6 and TNF-α, and it is considered reasonable that CAFs are induced by Ca.-CM and CAF-CM." (PMID 33659044, 2021). "All together, our study proposes ERK5 as a promising target for cancer therapies in light of the fact that ERK5 modulated not only the cancer cell viability but also the IL-6 production." (PMID 34671021, 2021). "The findings demonstrate that IL-6 promotes the development of breast, colorectal, pancreatic, and skin cancers." (PMID 34834397, 2021). "These numbers do not allow us to draw any convincing correlation between the level of IL-6 in the stroma and the level of autophagy in cancer cells." (PMID 33925189, 2021). "Patients with cancer had a more serious inflammation condition as indicated by a higher level of IL-6." (PMID 33746945, 2021). "Interleukin-6-class cytokines (e.g., IL-6, LIF, OSM, IL-11) are among few growth factors that are considered master regulators of cancer-associated inflammation." (PMID 34491463, 2021). "IL6 and GDF15 are important mediators of cancer cachexia with therapeutic relevance, since blocking either IL6 or GDF15 resulted in improved disease outcomes in cachectic animals." (PMID 35008253, 2021). "IL-6 is an inflammatory factor widely reported to be involved in several pathological networks in cancer, and is also recognized as an activator of the STAT3 signalling pathway." (PMID 33855091, 2021). "Reported pleiotropic activity of IFN-γ and IL-6 has also unveiled dysregulation of these cytokines in the pathogenesis of cancer." (PMID 34504657, 2021). "IL-6 produced by different cell types in the cancer microenvironment stimulates migration of cancer stem cells, hence the metastatic potential increases." (PMID 34681685, 2021). "The siRNA-loaded NPs significantly inhibited the IL-6/STAT3 expression, which was associated with blockade of proliferation, colony formation, migration, and angiogenesis in the cancer cells." (PMID 34502560, 2021). "Among IL6 transcriptional targets, many genes involved in the different cancer hallmarks have been described." (PMID 34422669, 2021). "The usefulness of anti-inflammatory cytokine therapies such as anti-TNFα therapy, anti-IL6 therapy, and anti-IL1α therapy on cancer cachexia have been reported." (PMID 34445197, 2021). "In the present study, M2-macrophages polarized by EVs also secreted IL-6 to promote malignancy of cancer cells." (PMID 33509150, 2021). "IL-6 secreted by cancer cells impaired the IL-12p70 secretion from DCs, which in turn had an effect on the differentiation of CD4+ T cells." (PMID 34671021, 2021). "IL-6 and IL-1 cause activation of STAT3, which can induce proliferation of cancer cells and migration via increased expression of matrix metalloproteinases." (PMID 34988471, 2021). "The pathway downstream of IL-10 includes Janus kinase and STAT, indicating that IL-10 promotes cancer progression and metastasis in the same way as IL-6." (PMID 33578830, 2021). "For example, suramin, an antagonist of the IL-6 receptor, markedly decreased the rate of cachexia in mice with C26 tumors, while neutralizing antibodies against IL-6 decreased muscle wasting muscle in rats with cancer cachexia." (PMID 34944037, 2021). "By secreting of IL-6, cancer cells inhibit IL-12p70 secretion from human moDCs, and the capacity of this modulated moDCs to induce a Th1 response is impaired." (PMID 34671021, 2021).